IFNG (interferon gamma)
Diseases named in the same sentence as IFNG in open-access papers (continued):
Sharing a sentence is not in itself a finding about the gene and the disease.
COVID-19 (continued). "In COVID-19, the immune system overreacts, leading to the release of large quantities of pro-inflammatory cytokines such as interleukin-6, tumour necrosis factor-alpha, and interferon-gamma." (PMID 38241342, 2024). "In addition to the high levels of IL-18, IL-1R7 is also found to be highly expressed in cell-to-cell communication among immune cells in COVID-19 patients and an elevated IFNγ was also observed." (PMID 38983847, 2024). "While recent studies have shown that patients with severe COVID-19 tend to have lower levels of interferon-gamma (IFN-γ) compared to those with milder forms of the disease, in our analysis IFN-γ shows a moderate (non-significant) increase with disease severity." (PMID 39845955, 2024). "Unlike the rapid immune response during the early infection stage, a gene set enrichment analysis showed that patients with long-term COVID-19 exhibited significantly reduced immune activity, especially in IFNγ and TGFβ, while other metabolic pathways were not significantly changed." (PMID 39202702, 2024). "However, a case series by van Laarhoven and colleagues showed that for severely immunocompromised patients that were critically ill with COVID-19 administration of IFNγ was therapeutically beneficial and reduced viral loads." (PMID 38950078, 2024). "The implication of multiple assays that involve IL-17 and IFNγ detection in COVID-19 patients could distinguish those who could develop MIS-C in the future." (PMID 39594853, 2024). "The association with symptomatic COVID-19 and the absence of an association signal for the *T allele of IFNG +874 with severity appears to be paradoxical." (PMID 38675991, 2024). "In this study, we screened for c-aAb targeting IFNα, IFNβ, IFNγ, IL-1α, IL-6, IL-10, and GM-CSF in the Surviving Pneumonia Study cohort, comprising 665 patients with CAP caused by COVID-19, influenza virus, bacteria, or unknown pathogen." (PMID 39606243, 2024). "There was also IFNG (IFN-γ gene) upregulation in T cells in patients with COVID-19." (PMID 39567718, 2024). "IL6R, TLR4, TLR2, and IFNG may be potential pathogenic genes and therapeutic targets for the CRS associated with COVID-19." (PMID 38165854, 2024). "Similarly, the same combination of cytokines has been described as an effective approach to induce cell death in cancer cells, and high levels of TNFα and IFNγ are supposed to be responsible for the inflammatory cell death in severe COVID-19 patients." (PMID 38542436, 2024). "Several clinical studies have shown IFNγ levels are correlated with COVID-19 disease severity." (PMID 38950078, 2024). "Similarly to COVID-19, in other ARVIs, the levels of IFNγ-inducible CXCL10 in BAL and plasma correlate with the severity of the disease." (PMID 37214455, 2023). "Therefore, future studies with specific questionnaires and tests on immune system function, such as leukocyte numbers and levels of interferon-gamma (IFN-γ), are warranted to shed more light on COVID-19 and reproductive health of uninfected men." (PMID 36890443, 2023). "To assess whether SARS-CoV-2 infection affects the maternal and fetal IFN secretion, we compared IFNγ levels in maternal blood and in cord blood in a pregnant population affected by COVID-19." (PMID 36677515, 2023). "However, the number of NK cells in COVID-19 patients with severe symptoms is negatively correlated with IFNγ concentration." (PMID 37264110, 2023). "Among them, several of the classical inflammatory markers, e.g., IL6, IL8, IL10, IL12B, TNF, and IFNγ had substantially higher levels in sepsis compared to COVID-19, leading to the conclusion that the inflammatory response is more pronounced in sepsis regardless of etiology or focus of infection." (PMID 36829233, 2023). "Overall, severe COVID-19 might be characterized by dysregulation in IFNγ, IFNλ and TLR3, 7 and 8 production." (PMID 36985262, 2023). "Also, interferon-gamma )IFNγ( producing CD4+ T cells from severe COVID-19 patients are lower than moderate cases." (PMID 37264452, 2023).
COVID-19 (continued). "A recent study has also showed that aging can alter several cytokines expression during COVID-19; in particular, hospitalized COVID-19 with > 70 years (n = 23) were characterized by increased serum IL-6 levels and decreased serum IFNγ levels, compared hospitalized COVID-19 with < 60 years (n = 26)." (PMID 36941580, 2023). "Furthermore, PBMCs isolated from severe COVID-19 patients at the acute phase of disease produced higher levels of IL-21, IFNγ, IL-4, and IL-17 in response to spike and RBD, than PBMCs from mild patients." (PMID 37061513, 2023). "The study also determined that Treg cell responses during COVID-19 may lead to more severe outcomes in humans, which is seemingly contradictory considering IFNγ- and IL-21-expressing T cells appeared to contribute to immunopathology." (PMID 37856551, 2023). "On the other hand, older patients, who are usually characterized by severe COVID-19, were noted to have decreased levels of IFNγ-producing virus-specific cells, which also indirectly indicates an important role of Th1 cells in the development of an effective immune response." (PMID 38179278, 2023). "Based on our data, it does not seem possible to determine a reliable threshold of robust immunity, but we suggest that high titres of neutralizing capacity and interferon-gamma response might be an indicator of protection against severe COVID-19 courses." (PMID 37830111, 2023). "All the data suggested that the booster vaccination of aerosolized Ad5-nCoV could induce a strong and durable spike-specific IFNγ response against SARS-CoV-2 in individuals primed with inactivated COVID-19 vaccines." (PMID 37868993, 2023). "However, significantly higher levels of IL-1β, TNF and IFNγ were found in semen from patients recovered from mild and/or severe COVID-19 with respect to control individuals (p < 0.05, p < 0.05 and p < 0.001, respectively)." (PMID 37497433, 2023). "In particular, IFNγ and IFNγ/IL-9 ratios are powerful biomarkers of COVID-19 severity and may predict the potential for survival." (PMID 37569646, 2023). "In a smaller proportion of individuals, severe COVID-19 may be driven by pre-existing anti-interferon gamma (anti-IFN-γ) autoantibodies." (PMID 37310006, 2023). "IFNGR1, the receptor for IFNG, was significantly reduced in the obese patients with COVID-19." (PMID 37361874, 2023). "A limitation of this study is the lack of data on the cellular immune response to vaccination with BNT162b2 (e.g., evaluation of IFNγ levels by COVID-19-specific Quantiferon assay), so we cannot analyze at this moment the effect of genetic background on the specific cellular immune response." (PMID 36851291, 2023). "Also, acute COVID-19 children had significantly elevated levels of cytokines, IFNγ, IL-2, TNFα, IFNβ, IL-6, IL-12, IL-17A and Granulocyte-Colony Stimulating Factors G-CSF in comparison to control children." (PMID 37013538, 2023). "In COVID-19, cytokine storms are triggered by the action of IFNγ, TNFα, IL-1, IL-2, and IL-6." (PMID 34436742, 2022). "Furthermore, COVID-19 vaccines induce T cell responses which can be evaluated by IFNγ release, IL-2 release, or both." (PMID 36105809, 2022). "Furthermore, CD4+ T cells also express interferon-gamma (IFN-gamma), a cytokine able to inhibit viral replication; however, seriously ill COVID-19 patients show reduced IFN-gamma-producing CD4+ T cells compared to convalescent individuals." (PMID 35860236, 2022). "COVID-19 patients have high levels of proinflammatory cytokines, including interleukin (IL)-1β, IL-6, IL-8, interferon-gamma (IFNγ), 10 kD interferon-gamma-inducible protein (IP-10), and monocyte chemoattractant protein-1 (MCP-1, CCL-2), which probably activate T-helper-1 (Th1) cell responses." (PMID 36294868, 2022). "Immune checkpoint molecules, such as PD-L1, sTIM3-3 and IFNγ, play an important role in regulating the host immune response and, for unknown reasons, are down-regulated in COVID-19." (PMID 35496309, 2022).
COVID-19 (continued). "Levels of IL-6, CXCL10, CXCL11, IFNγ and MCP-3 were > fourfold higher in the serum of patients with COVID-19 versus healthy controls and linked with observations of inflammatory and viral-induced interferon response genes detected in nasopharyngeal swab samples from the same patients." (PMID 35303909, 2022). "Conversely, T-cell exhaustion measured by IFNγ does not seem to differentiate severe COVID-19 from other infective causes of respiratory failure." (PMID 36016305, 2022). "However, as the authors explained the inhibitory effect of SARS-CoV-2-ORF6 on MHC class I suppression can be observed only under IFNγ treatment and thus cannot explain the downregulation observed in COVID-19 patients." (PMID 36325330, 2022). "From 8-10 to 14-16 weeks, the proportion of positive severe patients was maintained at approximately 80%, while the proportion of positive mild patients declined from 66.7% to 28.6%, indicating that IFNγ-secreting SARS-CoV-2-specific T cells gradually disappear in mild COVID-19 patients." (PMID 35663993, 2022). "Additional analysis of T-cell responses performed in the subset of NHRs that had a 3-month follow-up revealed that COVID-19 spike peptide stimulation led to specific activation and secretion of IFNγ, and that this response was more potent in humoral responders and impaired in humoral non-responders." (PMID 35214717, 2022). "Regardless of myopericarditis development, the COVID-19 mRNA vaccine caused an increase of NK cell number and gene expression associated with effector function such as IFN-γ (IFNG), granzyme A (GZMA), and granzyme B (GZMB) compared with healthy controls." (PMID 35251049, 2022). "Advanced disease is characterized by a hyper-inflammatory state, with high levels of circulating pro-inflammatory cytokines, such as Interleukin-6 (IL-6), Tumor Necrosis Factor-alpha (TNF-α) and interferon-gamma (IFN-γ), which have been blamed for the extensive COVID-19-related tissue damage." (PMID 36680091, 2022). "Moreover, RBD-specific humoral and cellular immunity were detected in COVID-19 convalescent individuals, where significant concentrations of nAbs, IgG and IgM as well as T cell-specific interferon gamma (IFN-γ) were present." (PMID 35287350, 2022). "Upon in vitro stimulation with anti-CD3/CD28 antibodies, CD4 T cells of COVID-19 patients showed a lower capacity to express IFNγ and IL-2 and proliferated together with the number of CFSElow cells (a measure of T-cell proliferation) compared to similar T-cell subsets of the control group." (PMID 35632823, 2022). "IFNγ-based therapy, while already employed as adjunctive immunotherapy in different bacterial, mycobacterial and fungal infections or sepsis-induced immunodepression, has been largely avoided in COVID-19 due to its potential proinflammatory effects." (PMID 36016305, 2022). "When analysis was performed using the O’Brien method and the functional groupings described in the Methods, we found that groups related to TH2 regulations (IL-4, IL-13, IL-33), cell metabolism (lep, lep-R) and interferons (IFNα, IFNβ, IFNγ) were also predictive of life-threatening COVID-19." (PMID 35386702, 2022). "Cytokine storm of interleukin (IL)-2, IL-4, tumor necrosis factor-alpha (TNF-α), interferon-gamma (IFN-γ), and C-reactive protein has not been directly associated with COVID-19, whereas IL-6 and IL-10 were found to be COVID-19 severity predictors." (PMID 35054524, 2022). "In addition, we found that cytokines related to TH2 regulations (IL-4, IL-13, IL-33), cell metabolism (lep, lep-R) and interferons (IFNα, IFNβ, IFNγ) were also predictive of life-threatening COVID-19." (PMID 35386702, 2022). "A detrimental role for cytokines, specifically IFNγ and TNF, had been previously associated with severe COVID-19 and experimentally identified as a risk factor for severe disease in SARS-CoV-2-infected KRT18-hACE2 mice by causing a form of inflammatory cell death termed PANoptosis." (PMID 35023830, 2022).
COVID-19 (continued). "NK cells from COVID-19 patients show reduced expression of IFNγ and TNFα." (PMID 38566903, 2022). "However, some reports found that T cells in COVID-19 patients, including those with severe disease, expressed substantial amounts of IFNγ, IL-17, FASLG, Granzyme A and perforin." (PMID 33575657, 2021). "TGB, as a substrate for CYP3A4, may be susceptible to the interaction with COVID-19 vaccines due to interferon-gamma production from T-cell responses elicited by COVID-19 vaccines." (PMID 34502487, 2021). "Indeed, low IFNγ and low induction of interferon-stimulated genes contribute to the development of COVID-19." (PMID 34936684, 2021). "We conducted a prospective, cross-sectional analysis in COVID-19 recovered patients at various time points over a 10-month period in order to investigate how circulating antibody levels and interferon-gamma (IFN-γ) release by peripheral blood cells change over time following natural infection." (PMID 34646805, 2021). "Altogether, these results suggest that both pulmonary and extrapulmonary tissues may play important role in the dysregulated levels of interleukins (e.g. IL-6 and IL-1), interferon-gamma, and tumor necrosis factor superfamily cytokines in COVID-19 patients." (PMID 34262555, 2021). "Taken together, these studies suggest that IFNγ or its precursors, such as interleukin-18, interleukin-12 or interleukin-23, could have a role in COVID-19." (PMID 34911594, 2021). "Moreover, IFNG hub-high traffic gene neutralizers have been predicted as antagonists of COVID-19 biology." (PMID 34975885, 2021). "GSEA analysis identified interferon alpha response and interferon gamma response pathway genes enriched in all B cell subsets in individuals with COVID-19, and this was more marked in those with asymptomatic or mild disease, and attenuated in severe and critical disease." (PMID 33879890, 2021). "However, in the abscence of cetuximab, a significant reduction of IFNγ secretion was observed in NK cells from COVID-19 patients compared with healthy donors." (PMID 33060840, 2021). "Moreover, CO2 treatment is the most effective method for inactivating ERK1/2 in epithelial cells in the presence of increased IFNγ and TNFα levels, which is characteristic of severe COVID-19." (PMID 34741187, 2021). "Instruments for interleukin-12 and −23, and for IFNγ could only be obtained from GWAS included in the COVID-19 GWAS, possibly biasing towards the confounded estimates." (PMID 34911594, 2021). "However, in a recent in-press study from China involving 36 COVID-19 patients, 13 (36%) had interferon-gamma release assay (IGRA) positivity." (PMID 34966601, 2021). "In contrast, serum IFNγ levels were significantly increased in the severe COVID-19 group." (PMID 34858405, 2021). "Other roles of T cells besides IFNγ production may contribute to the better prognosis of women with COVID-19." (PMID 34434199, 2021). "ERK1/2 activated by the combined action of RBD and cytokines crucial for the development of severe COVID-19, i.e. interferon-gamma (IFNγ) and tumour necrosis factor-α (TNFα), are more effectively inactivated by CO2 than by dexamethasone or acetylsalicylic acid in human bronchial epithelial cells." (PMID 34741187, 2021). "During a cytokine storm in COVID-19, several inflammatory cytokines are quickly formed, including interleukin 6, tumor necrosis alpha, interleukin 1β, interleukin 12, and interferon gamma, stimulating the secretion of ferritin by hepatocytes, Kupffer cells, and macrophages." (PMID 34840966, 2021). "The severe phase of COVID-19 is characterised by a high level of expression of interferon-stimulated genes with proinflammatory activities, showing the immunopathological role of IFNγ response." (PMID 34639073, 2021).
COVID-19 (continued). "Recent in-vitro data from COVID-19 patients with active pulmonary tuberculosis has shown an attenuated interferon-gamma response after stimulation of whole blood with peptides derived from SARS-CoV-2 spike protein, in contrast to a normal response to Mycobacterium tuberculosis-specific antigens." (PMID 34673822, 2021). "The matched quality of response but the higher threshold for IFNγ production by T cells in children may drive a less inflammatory environment that promotes more mild COVID-19 outcomes in children." (PMID 34326343, 2021). "Peripheral blood mononuclear cells of 37 patients with mild, severe and critical COVID-19 and 10 healthy individuals were analyzed by IFNγ ELISpot and multi-color flow cytometry upon stimulation with peptide pools covering complete immunodominant SARS-CoV-2 matrix, nucleocapsid and spike proteins." (PMID 34194438, 2021). "The analysis of COVID-19 lung samples has revealed a dramatic upregulation of the interferon gamma (IFNγ) protein, which may be accompanied by a large innate immune response." (PMID 33791293, 2021). "It has been elucidated that the prognosis of COVID-19 could be worsened by the secretion of pro-inflammatory cytokines, including interleukins, IFNγ, and TNF-α." (PMID 34202374, 2021). "Moreover, IL-18 and IL-1R7 are found to be highly expressed in cell-to-cell communication among immune cells in COVID-19 patients and elevated IFNγ was observed in COVID-19 patients in line with increased IL-18 levels." (PMID 33823154, 2021). "Other cytokines also involved in Th1 differentiation and survival such as IL-12 were reduced 4.0- and 3.7-fold in patients with severe (p<0.05) and critical (p<0.01) COVID-19, respectively, as well as IFNγ, which was also reduced 3.4- and 1.6-fold, respectively." (PMID 34122423, 2021). "In particular, we investigated its ability to bind to IFNγ and IL-6 cytokines and inhibit their signalling pathways that allows for modulation of the development of a cytokine storm, including in patients with acute COVID-19." (PMID 34639073, 2021). "Notably, depletion of IFNγ secreting CD4+ T cells has been reported in hospitalized COVID-19 patients with a trend towards a greater reduction in severe disease." (PMID 34113347, 2021). "However, COVID-19-recovered older participants (n = 51) had greater antibody and T-cell responses, including IFNγ+ and IFNγ+IL-2+TNFα+-specific CD4+ T cells (p < 0.0001), as well as TNFα+-specific CD8+ T cells (p < 0.001), than COVID-19-naive older adults." (PMID 34868051, 2021). "In addition, more genes involved in “type I interferon” and “interferon-gamma” pathway showed downregulation in COVID-19 patients (both PCov and NCov)." (PMID 34326311, 2021). "Previous reports have shown that SARS-CoV-2 peptide stimulation significantly induces IFNγ production by CD4+ T cells from unexposed individuals and that the Th1 response is associated with an effective resolution of infection and symptoms in COVID-19." (PMID 35822004, 2021). "Likewise, proteomic profiling approaches and targeted analysis of plasma proteins have shown high IL-6, IL-10, IL-8 and IFNγ levels in many COVID-19 patients." (PMID 33239683, 2020). "Also, that IL-6, IL-10 and interferon-gamma that are elevated in KD as well as in COVID-19, where these are shown to exert an inflammatory-mediated lung injury." (PMID 33162899, 2020). "There are some suggestions that impaired cellular immunity through a reduction in Th1 response and IFNG (interferon gamma) expression, as well as cross-reactivity with common cold coronaviruses, might be involved in the differential COVID-19 course." (PMID 33198287, 2020). "Several drugs commonly used to treat COVID-19 patients were tested for their potential to restore cytokine balance in vitro, notably to increase IFNγ production and decrease the production of inflammatory cytokines, while keeping the secretion of regulatory cytokines constant." (PMID 33585507, 2020).